OR5AC2 (olfactory receptor family 5 subfamily AC member 2)
Description:
Odorant receptor.
Synonyms: HSA1
Tractability: Antibody: UniProt places it where antibodies can reach, with medium confidence; UniProt predicts a signal peptide or a membrane-spanning region; its Gene Ontology location is reachable by antibodies, with medium confidence.
Gene: Protein-coding gene on chromosome 3 (98,087,173 to 98,088,102, forward strand). Ensembl gene ENSG00000196578.
Subcellular location: Cell membrane
Pathways (Reactome):
Sensory Perception: Expression and translocation of olfactory receptors
Gene Ontology:
Molecular function: odorant binding; olfactory receptor activity; G protein-coupled receptor activity
Biological process: sensory perception of smell; detection of chemical stimulus involved in sensory perception of smell; G protein-coupled receptor signaling pathway
Cellular component: membrane; plasma membrane
Genetic constraint (gnomAD): Loss-of-function variants: 0 observed, 0.0766 expected, observed/expected ratio (o/e) 0, 90% interval 0 to 1.89. That is too few expected variants to judge how well the gene tolerates losing a copy. Missense variants: 446 observed, 390.44 expected, observed/expected ratio (o/e) 1.14, 90% interval 1.06 to 1.24. Synonymous variants: 170 observed, 143.68 expected, observed/expected ratio (o/e) 1.18, 90% interval 1.04 to 1.34.
Homologues: Orthologues: dog OR5AC26 (75% identical), mouse Or5ac16 (69% identical), mouse Or5ac20 (69% identical), rat Olr1537 (68% identical), mouse Or5ac19 (66% identical), mouse Or5ac17 (64% identical). Paralogues in human: OR5H2 (64% identical), OR5H1 (61% identical), OR5H14 (61% identical), OR5H6 (60% identical), OR5H15 (59% identical), OR5K4 (52% identical), OR5K1 (51% identical), OR5K3 (49% identical), OR5K2 (49% identical), OR5H8 (49% identical), OR8B12 (48% identical), OR8B3 (47% identical), and 84 more.